TYK2 (tyrosine kinase 2)
Diseases named in the same sentence as TYK2 in open-access papers (continued):
Sharing a sentence is not in itself a finding about the gene and the disease.
diabetes (23 papers, 2015 to 2025). "We revealed that a loss of Tyk2 in the host environment led to a reduced incidence of diabetes induced by Tyk2+/− splenocytes compared with those in wild type host NOD.SCID mice (P = 0.003)." (PMID 38351043, 2024). "Meanwhile, in T2DM, the TYK2 promoter variant was linked to an increased incidence of diabetes and associated with dysfunctional insulin production, whereas the T allele of COL4A3 was associated with T2DM with a protective role." (PMID 38926794, 2024). "We previously reported that reduced Tyk2 expression in β-cells led to impaired antiviral defense, increasing the risk of β-cell-tropic virus-induced diabetes in mice." (PMID 38351043, 2024). "In contrast to the role of TYK2 in autoimmune T1D described in this paper, we reported that reduced TYK2 expression was a risk factor for β-cell tropic virus-induced diabetes and impaired insulin secretion." (PMID 38351043, 2024). "A recent report suggests that rare loss-of-function TYK2 promoter mutations are associated with increased diabetes susceptibility in the Japanese population." (PMID 36289205, 2022). "Polymorphisms in TYK2, a type I interferon receptor signaling molecule, confer risk for the development of diabetes." (PMID 34822454, 2021). "In our previous study, it was reported that mice with Tyk2 deficiency against a B6 background challenged with 1 × 103 PFU of EMCV-D developed diabetes." (PMID 32727064, 2020). "The TYK2 promoter variant showed reduced promoter activity of the TYK2 gene and an association with the risk of T1D; in particular, in patients with T1D it was associated with flu-like syndrome at diabetes onset and GADA-negativity." (PMID 32727064, 2020). "The irradiated Tyk2-deficient mice that were transferred spleen cells derived from either WT or Tyk2-deficient mice developed diabetes, whereas the irradiated WT mice that received spleen cells from either WT or Tyk2-deficient mice showed resistance." (PMID 32727064, 2020). "TYK2 promoter variant serves as a risk not only in T1D but also in T2D, suggesting that TYK2 promoter variant is associated with an overall risk for diabetes." (PMID 28826655, 2017). "In Subtype 2, a significantly higher incidence was observed in T1D cases carrying the TYK2 promoter variant (OR, 2.60; 95%CI, 1.03–6.97; p = 0.032), and also showing a flu-like syndrome at diabetes onset (OR, 2.34; 95%CI, 1.27–4.35; p = 0.003)." (PMID 28826655, 2017). "Recently, we reported that TYK2 promoter variant serves as a putative virus-induced diabetes susceptibility gene associated with deteriorated interferon-dependent antiviral response." (PMID 28826655, 2017). "In conclusion, this manuscript reports the identification of the murine natural virus-induced diabetes susceptibility gene as Tyk2, and demonstrates that Tyk2 gene expressed in pancreatic β-cells controls susceptibility to virus-induced diabetes." (PMID 25849081, 2015). "Recently, natural mutation of Tyrosine kinase 2 (Tyk2) gene has been shown to determine susceptibility to murine virus-induced diabetes." (PMID 26288847, 2015). "We report here that novel Tyrosine kinase 2 (Tyk2) gene mutations are present in virus-induced diabetes-sensitive SJL and SWR mice." (PMID 25849081, 2015). "The TYK2 promoter variant is associated with an overall risk for diabetes, serving a good candidate as a virus-induced diabetes susceptibility gene in humans." (PMID 26288847, 2015). "Here the authors show that mutations in Tyk2 gene underlie susceptibility to virus-induced diabetes in mice, due to Tyk2 requirement for antiviral response in insulin-producing cells." (PMID 25849081, 2015). "We thus examined the association of TYK2 gene polymorphisms with T1D and type 2 diabetes (T2D), focusing on association with flu-like syndrome at diabetes onset." (PMID 26288847, 2015). "Interestingly, reduced expression of the TYK2 gene in pancreatic β-cells is a contributing factor to virus-induced susceptibility to diabetes." (PMID 38699234, 2024).
diabetes (continued). "Moreover, the recovery of Tyk2 gene expression specific to β-cells in the Tyk2-deficient B6 mice was sufficient to prevent diabetes onset." (PMID 32727064, 2020). "Thus, reduced Tyk2 gene expression in pancreatic β-cells due to natural mutation is responsible for susceptibility to virus-induced diabetes." (PMID 25849081, 2015). "Thus, the TYK2 promoter variant was more frequent in all patients with diabetes compared with healthy controls (OR, 2.3; 95% CI, 1.2 to 4.1; P = 0.009)." (PMID 26288847, 2015). "In the present study, we could, for the first time to the best of our knowledge, identify the natural susceptibility gene as Tyk2 to EMC virus-induced diabetes in mice." (PMID 25849081, 2015). "This pattern of data suggests that a TYK2 variant may be more likely associated with susceptibility to virus-induced diabetes appearing as fulminant diabetes in human beings, observed in Japan more frequently, rather than associated with autoimmune T1D." (PMID 26288834, 2015). "Thus, it was concluded that Tyk2 KO mice had high susceptibility to EMC-D virus-induced diabetes, challenged by intraperitoneal route." (PMID 25849081, 2015). "Since Tyk2 gene KO mice were highly susceptible to EMC-D virus-induced diabetes we screened for mutations of the Tyk2 gene in virus-induced diabetes-sensitive DBA/2J (DBA), SJL/J (SJL) and SWR/J (SWR) mice as well as resistant B6, C3H/HeJ and moderately susceptible A/J, and BALB/cJ mice." (PMID 25849081, 2015). "All these observations taken together indicate that the TYK2 gene might be regarded as a good candidate for the virus-induced diabetes susceptibility gene in humans." (PMID 26288847, 2015). "Since we showed the significance of mutations of the Tyk2 gene in the susceptibility to virus-induced diabetes, we next investigated whether mutations of the Tyk2 gene affect expression level of the Tyk2 gene." (PMID 25849081, 2015). "Among the susceptible strains of mice, DBA/2 mice, which are also highly susceptible to EMC-D virus-induced diabetes, lack Tyk2 gene mutation, indicating that genes other than Tyk2 may be responsible for increased susceptibility to virus-induced diabetes." (PMID 25849081, 2015). "Transcriptional phenotyping of pancreatic islets, pancreatic lymph nodes, and spleen highlighted a role for TYK2 inhibition in modulating signalling pathways associated with inflammation, translational control, stress signalling, secretory function, immunity, and diabetes." (PMID 40335415, 2025). "However, based on our results, the partial loss of TYK2 expression could lead to a lower β-cell mass as a contributing factor to the increased diabetes risk." (PMID 36289205, 2022). "Since TYK2 promoter variant serves as a higher risk for the development of diabetes, TYK2 promotor variant positive young healthy people may develop diabetes along with aging, and thus the rate of TYK2 promoter variant will become lower in older-aged people." (PMID 28826655, 2017). "Interestingly, highly virus-induced diabetes-susceptible DBA mice have the WT Tyk2 gene." (PMID 25849081, 2015). "We found Tyk2 gene mutations at the promoter region (−678_−674 5A>5T, −713T>C, −735 C>T, −919 G>T, −938_−930 del 9T, −998 G>C, −1010T>C, −1015 C>T, −1219A>G) from transcription start point at exon 1 and exons 9592A>G and 10642A>G only in virus-induced diabetes-sensitive SJL and SWR mice." (PMID 25849081, 2015). "As expected, the incidence of diabetes was reduced in Tyk2−/− mice (15.3%) compared with their Tyk2+/+ (78.5%) and Tyk2+/− (90.0%) littermates." (PMID 38351043, 2024). "At 14w, a reduced number of islets with insulitis were observed in Tyk2−/− mice compared with age-matched Tyk2-sufficient littermates, consistent with the reduction of diabetes incidence in Tyk2−/− NOD mice." (PMID 38351043, 2024).
diabetes (continued). "NOD.SCID mice, which lack T and B cells, adoptively transferred with Tyk2+/− splenocytes developed diabetes within nine weeks after transfer, whereas mice receiving Tyk2−/− splenocytes had reduced diabetes incidence irrespective of the donor age." (PMID 38351043, 2024). "Although the role of TYK2 in virus-induced β-cell destruction is controversial, these observations suggest that TYK2 is involved in the pathogenesis of diabetes induced by virus." (PMID 38351043, 2024). "Mice carrying a mutant Tyk2 fail to respond to type I interferon appropriately, leading to a failed β-cell antiviral response and sensitization to virus-induced diabetes." (PMID 34822454, 2021). "We found that EMCV-D induced diabetes in susceptible strains, SJL and SWR, harboring a mutated Tyk2 gene." (PMID 32727064, 2020). "While diabetes is a rare feature of monogenic interferonopathies, two loci within the IFN pathway (IFIH-1 and TYK2) have been robustly associated with polygenic T1D." (PMID 30888520, 2019). "We carried out intraperitoneal challenge with 1.0 × 103 plaque-forming unit of EMC-D virus to Tyk2 gene knockout (Tyk2 KO) and wild-type (Tyk2 WT) male mice with virus-induced diabetes-resistant C57BL/6J (B6) background, and measured blood glucose levels." (PMID 25849081, 2015). "A separate study from our group presented experimental evidence that the Tyk2 gene, an interferon receptor signaling pathway molecule, was responsible for encephalomyocarditis (EMC) virus-induced diabetes susceptibility in mice." (PMID 26288847, 2015). "Tyk2 gene mutation in diabetes-sensitive SJL and SWR mice is closely associated with significantly reduced Tyk2 gene expression including that in pancreatic β-cells." (PMID 25849081, 2015). "Mice carrying the mutant Tyk2 gene on the virus-resistant C57BL/6 background are highly sensitive to virus-induced diabetes." (PMID 25849081, 2015). "In addition, the timing of diabetes onset was delayed in Tyk2−/− mice (22 weeks of age (22w)) compared with their Tyk2+/+ (15w) and Tyk2+/− (16w) littermates." (PMID 38351043, 2024). "Comparable diabetes development was observed between Tyk2+/+ and Tyk2+/− mice." (PMID 38351043, 2024). "Only those patients without anti-GAD Ab or elevated IgE were associated with TYK2 promoter variant and with flu-like syndrome at the diabetes onset, suggestive of association with virus-induced diabetes." (PMID 28826655, 2017). "Since SJL mice carry the susceptible Tyk2 gene mutation as shown by this study, the SJL mouse model may be an appropriate animal assay system to simulate human virus-induced diabetes susceptibility." (PMID 25849081, 2015). "Highly virus-induced diabetes-susceptible strains such as SJL and SWR mice possessing a mutated Tyk2 gene, which is associated with reduced expression of Tyk2 gene in pancreatic β-cells, were prone to the development of diabetes caused by the diabetogenic strain of EMC-D virus." (PMID 26288847, 2015). "In addition, the importance of intact Tyk2 gene expression in pancreatic β-cells in the resistance against EMC-D virus-induced diabetes was revealed by the MIP-Tyk2 transgenic mice crossed with Tyk2 KO or Tyk2-mutated mice." (PMID 25849081, 2015). "In addition, high-dose IFN-α treatment after EMCV-D infection did not inhibit diabetes onset, suggesting that Tyk2-deficient mice were refractory to high-dose IFN." (PMID 32727064, 2020). "Taking these findings together, we concluded that β-cell-specific Tyk2-mediated antiviral responses through type 1 IFN stimulation are important for preventing VID, and the Tyk2 gene is a gene variant represented in SJL and SWR mice that naturally confers susceptibility to EMCV-D-induced diabetes." (PMID 32727064, 2020). "Reversal of virus-induced diabetes could be achieved by β-cell-specific Tyk2 gene expression." (PMID 25849081, 2015).
diabetes (continued). "Since the outcome of virus-induced diabetes is influenced by many factors including viral diabetogenicity and host susceptibility, the discovery of other risk genes associated with virus-induced diabetes in addition to IFIH1 and TYK2 genes is both possible and feasible." (PMID 26288847, 2015). "We demonstrate that allosteric TYK2 inhibition blocked IFN-mediated transcriptional responses in vitro and delayed the onset of diabetes in preclinical murine models of T1D." (PMID 40335415, 2025). "All irradiate diabetic Tyk2 KO mice that received WT or KO spleen cells died by 14 days after infection, while WT mice receiving either WT or Tyk2 KO mice derived spleen cells could escape from the development of diabetes, and could survive until 3 weeks after infection." (PMID 25849081, 2015). "Even though the overall incidence of diabetes was not reduced, mice treated with the TYK2 inhibitor from 12w had a delayed onset of T1D compared with vehicle treated mice." (PMID 38351043, 2024). "As controls, we also used a nondiabetogenic strain of EMC-B virus, and found that the virus did not induce diabetes even in Tyk2 KO mice." (PMID 25849081, 2015). "The finding was consistent with the in vivo experiments above in EMC-D virus-infected Tyk2 KO mice, which showed the ineffectiveness of an increased IFN level to rescue virus-induced β-cell damage, and failed to prevent the development of diabetes." (PMID 25849081, 2015). "Taken overall, these results indicate that Tyk2 expression in parenchymal cells, not in splenic immune cells, is important to resist against EMC-D virus-induced diabetes." (PMID 25849081, 2015).
Crohn disease (20 papers, 2012 to 2025). A gastrointestinal disorder characterized by chronic inflammation involving all layers of the intestinal wall, noncaseating granulomas affecting the intestinal wall and regional lymph nodes, and transmural fibrosis. "For example, an eQTL for TYK2 specifically detected in 16 h-stimulated TEM cells colocalized with a Crohn’s disease association." (PMID 35618845, 2022). "Here, we show a similar effect, where individuals carrying a protective allele for Crohn’s disease have lower expression of TYK2 in TEM cells at 16 h of activation." (PMID 35618845, 2022). "Consistent with previous reports in Crohn’s disease, the TYK2 I684S variant was associated with increased risk of IBD in our dataset (OR = 1.26 [1.10–1.43], P = 8x10-4)." (PMID 25849893, 2015). "Similarly, a TYK2 eQTL detected in TEM cells colocalizes with a Crohn’s disease GWAS association." (PMID 35618845, 2022). "The two SNPs for Crohn’s disease are rs12720356 and rs4077515 whose host genes (TYK2 and CARD9) rank 14th and 354th by GenePANDA." (PMID 28252032, 2017).
multiple sclerosis (18 papers, 2016 to 2025). A progressive autoimmune disorder affecting the central nervous system resulting in demyelination. "In murine studies, TYK2-deficient mice have been found to be protected against disease development in experimental models of multiple sclerosis and Ps, with Th17 cells being differentiated in these mice through failed response to IL-23 stimulation." (PMID 39684939, 2024). "The MBP gene encodes a transmembrane IgE receptor associated with susceptibility to multiple sclerosis (OMIM#126200) and the TYK2 gene encodes a tyrosine kinase associated to type I and III interferon signaling, playing a role in antiviral immunity." (PMID 33815474, 2021). "Two of these variants (TYK2 p.Pro1104Ala, overall MAF 4.1% in our samples; GALC p.Asp84Asp, overall MAF 3.9%) are in regions identified by our latest MS GWAS and show linkage disequilibrium with the common-variant associations we have previously reported." (PMID 30343897, 2018). "One is a low-frequency missense variant in TYK2, another is a missense variant in MTHFR that reduces the function of the encoded enzyme affecting methionine metabolism, reported to be dysregulated in multiple sclerosis brain." (PMID 29263835, 2017).
breast cancer (17 papers, 2014 to 2026). A primary or metastatic malignant neoplasm involving the breast. "Although we observed nominal associations of genetically proxied TYK2 inhibition with prostate and breast cancer risk in both UK Biobank and FinnGen, the tissue-specific gene expression and colocalization analyses did not confirm these associations." (PMID 36842216, 2023). "Mice with knockout of Tyk2 were more susceptible to xenograft tumor growth and metastasis of breast cancer 4T1 cells, and Tyk-/- mice also developed leukemia and lymphoma at an increased rate, both likely due to defective tumor immunosurveillance." (PMID 34439323, 2021). "In agreement with this, 4T1 breast cancer cells with TYK2 deficiency demonstrate enhanced tumor growth and metastasis." (PMID 34439323, 2021). "Nonetheless, proteomics suggested that low TYK2 facilitates local metastasis in breast cancer, and a comprehensive screen for protein tyrosine kinase variants in numerous cancer cell lines identified splice variants that render TYK2 inactive." (PMID 31694222, 2019). "Finally, potential adverse effects of TYK2 inhibitors, including elevated risk of prostate and breast cancer, should be evaluated in studies with long follow-up duration." (PMID 36842216, 2023). "The study identified several potential adverse effects of TYK2 inhibitors, including headache, upper respiratory tract infection, nausea, diarrheal, increased circulating levels of creatinine and liver enzymes, and risk of certain malignant neoplasms, such prostate and breast cancer." (PMID 36842216, 2023). "Several potential adverse effects of TYK2 inhibitors, including headache, upper respiratory tract infection, nausea, diarrheal, increased circulating levels of creatinine and liver enzymes, and risk of certain malignant neoplasms, such prostate and breast cancer, should be further explored." (PMID 36842216, 2023). "An unusually high expression of TYK2 associated with or causative for carcinogenesis (reviewed) was described for various cancer cell lines and samples from patients suffering from prostate, ovarian, cervical, and breast cancer, as well as malignant peripheral nerve sheath tumors (MPNST)." (PMID 31694222, 2019). "Here we report a unique role of the JAK family kinase TYK2 in suppressing breast cancer metastasis under low ECM stiffness." (PMID 41882003, 2026). "A dissociable antibody microarray (DAMA) staining screen of hundreds of proteins, a technique that combines immunostaining and protein microarrays, found that TYK2 protein levels were elevated in breast cancer compared to normal breast cell-lines." (PMID 34439323, 2021). "A computational analysis found that the TYK2 rs34536443 variant (P1104A) conferred increased cancer risk, and this mutation was subsequently detected in several cancers, including MPNST, breast cancer, colon cancer, stomach cancer and AML." (PMID 34439323, 2021). "ODZ10117 did not significantly inhibit the JAK family of tyrosine kinases, including JAK1, JAK2, JAK3, and TYK2, in breast cancer cells and Hodgkin’s lymphoma cells." (PMID 31684051, 2019). "The role of TYK2 is confirmed by biological experiments in suppressing the growth and metastasis of breast cancer." (PMID 29179495, 2017). "The side effects of TYK2 inhibitors should be assessed, especially on prostate and breast cancer." (PMID 36842216, 2023). "There were nominal associations of genetically-proxied TYK2 inhibition with increased risk of prostate and breast cancer but not in tissue-specific expression MR or colocalization analyses." (PMID 36842216, 2023). "Furthermore, knockdown of TYK2 reduced migration of breast cancer cell lines." (PMID 31694222, 2019). "Furthermore, TYK2 inhibition could also block the invasiveness of breast cancer cells." (PMID 33731185, 2021).
breast cancer (continued). "In a series of recent genomic, proteomic, cell-based and mouse model studies, TYK2 has emerged as an oncogene that promotes migration, invasion and metastasis in multiple types of cancer, including stomach, MPNST, breast cancer, liver cancer, colon cancer, prostate cancer and lung cancer." (PMID 34439323, 2021).